PPP2CB (protein phosphatase 2 catalytic subunit beta)
Description:
Catalytic subunit of protein phosphatase 2A (PP2A), a serine/threonine phosphatase involved in the regulation of a wide variety of enzymes, signal transduction pathways, and cellular events (Probable). PP2A can modulate the activity of phosphorylase B kinase, casein kinase 2, mitogen-stimulated S6 kinase, and MAP-2 kinase. Part of the striatin-interacting phosphatase and kinase (STRIPAK) complexes. STRIPAK complexes have critical roles in protein (de)phosphorylation and are regulators of multiple signaling pathways including Hippo, MAPK, nuclear receptor and cytoskeleton remodeling. Different types of STRIPAK complexes are involved in a variety of biological processes such as cell growth, differentiation, apoptosis, metabolism and immune regulation.
Synonyms: PP2Abeta; PP2CB
Tractability: Small molecule: a drug acting on it is in phase 2 or 3 trials. PROTAC: UniProt records ubiquitination sites on it; ubiquitination databases record sites on it; its protein half-life has been measured.
Target class: Protein Phosphatase; Phosphatase; Serine/threonine protein phosphatase; Enzyme
Gene: Protein-coding gene on chromosome 8 (30,774,096 to 30,814,314, reverse strand). Ensembl gene ENSG00000104695.
Subcellular location: Cytoplasm; Nucleus; Chromosome, centromere; Cytoplasm, cytoskeleton, spindle pole
Subcellular location (Human Protein Atlas): Nucleoplasm
Pathways (Reactome):
Signal Transduction: Beta-catenin phosphorylation cascade; DARPP-32 events; Degradation of beta-catenin by the destruction complex; Disassembly of the destruction complex and recruitment of AXIN to the membrane; ERK/MAPK targets; ERKs are inactivated; Negative regulation of MAPK pathway; PI5P, PP2A and IER3 Regulate PI3K/AKT Signaling; RAF activation; RHO GTPases Activate Formins; Spry regulation of FGF signaling
Cell Cycle: Amplification of signal from unattached kinetochores via a MAD2 inhibitory signal; Cyclin A/B1/B2 associated events during G2/M transition; Cyclin D associated events in G1; EML4 and NUDC in mitotic spindle formation; Inhibition of replication initiation of damaged DNA by RB1/E2F1; MASTL Facilitates Mitotic Progression; Mitotic Prometaphase; Resolution of Sister Chromatid Cohesion; Separation of Sister Chromatids
Disease: APC truncation mutants have impaired AXIN binding; AXIN missense mutants destabilize the destruction complex; CTNNB1 S33 mutants aren't phosphorylated; CTNNB1 S37 mutants aren't phosphorylated; CTNNB1 S45 mutants aren't phosphorylated; CTNNB1 T41 mutants aren't phosphorylated; Signaling by GSK3beta mutants; Truncations of AMER1 destabilize the destruction complex
Immune System: Co-inhibition by CTLA4; Co-stimulation by CD28; PKR-mediated signaling
Metabolism: PP2A-mediated dephosphorylation of key metabolic factors; Regulation of glycolysis by fructose 2,6-bisphosphate metabolism
Hemostasis: Platelet sensitization by LDL
Gene Ontology:
Molecular function: protein binding; protein serine/threonine phosphatase activity; tau protein binding; hydrolase activity; phosphoprotein phosphatase activity; transmembrane transporter binding
Biological process: negative regulation of canonical NF-kappaB signal transduction; negative regulation of gene expression; negative regulation of tumor necrosis factor-mediated signaling pathway; mitotic cell cycle; protein dephosphorylation; regulation of neurofibrillary tangle assembly; response to lead ion; negative regulation of Ras protein signal transduction; regulation of microtubule polymerization
Cellular component: FAR/SIN/STRIPAK complex; nucleoplasm; cytosol; protein phosphatase type 2A complex; chromosome, centromeric region; cytoplasm; nucleus; spindle pole
Genetic constraint (gnomAD): Loss-of-function variants: 15 observed, 31.19 expected, observed/expected ratio (o/e) 0.48, 90% interval 0.32 to 0.74. The upper end of that interval is the gene's LOEUF score, 0.74, which puts it in group 3 of 6, group 1 being the genes least tolerant of losing a copy. Missense variants: 200 observed, 342.91 expected, observed/expected ratio (o/e) 0.58, 90% interval 0.52 to 0.66. Synonymous variants: 120 observed, 115.98 expected, observed/expected ratio (o/e) 1.03, 90% interval 0.89 to 1.2.
Homologues: Orthologues: chimpanzee PPP2CB (100% identical), dog PPP2CB (100% identical), macaque PPP2CB (100% identical), mouse Ppp2cb (100% identical), pig PPP2CB (100% identical), rat Ppp2cb (100% identical), guinea pig PPP2CB (99% identical), rabbit PPP2CB (99% identical), zebrafish ppp2cb (99% identical), tropical clawed frog ppp2cb (98% identical), Drosophila melanogaster mts (94% identical), Caenorhabditis elegans let-92 (89% identical). Paralogues in human: PPP2CA (97% identical), PPP4C (65% identical), PPP6C (59% identical), PPP1CA (48% identical), PPP1CB (48% identical), PPP1CC (48% identical), PPP3CA (41% identical), PPP3CB (41% identical), PPP3CC (40% identical), PPEF2 (35% identical), PPP5C (35% identical), PPEF1 (34% identical).
Diseases named in the same sentence as PPP2CB in open-access papers:
PPP2CB is named in the same sentence as 21 diseases in open-access papers, as found by Europe PMC text mining. Sharing a sentence is not in itself a finding about the gene and the disease. The quoted sentences say what the papers report.
breast carcinoma (4 papers, 2015 to 2024). "In addition, PRKAR1A and PPP2CB negatively correlated with miR-1246 expression, indicating that miR-1246 could regulate both targets in tumors of breast cancer patients." (PMID 28159925, 2017). "PPP2CB, PPP3CA, PPP3CB, PPP3CC and PPP6C were significantly expressed at lower levels in breast cancer tissues." (PMID 34964699, 2022). "In the Oncomine database, when compared with normal breast tissues, PPP1CA, PPP2CA, PPP4C and PPEF1 were significantly elevated in breast cancer tissues, while PPP1CB, PPP2CB, PPP3CA, PPP3CB, PPP3CC and PPP6C were significantly decreased in breast cancer tissues." (PMID 34964699, 2022). "Since miR-1246 was expressed higher in ER- breast cancer subtypes and induced pro-inflammatory responses in MSCs by targeting PRKAR1A and PPP2CB, we hypothesized potential roles of PRKAR1A and PPP2CB as tumor-suppressors in breast cancer." (PMID 28159925, 2017).
pancreatic cancer (2 papers, 2021). "Among all the PPPcs, PPP1CB, PPP1CC, PPP2CA, PPP2CB, PPP3CB, and PPP5C had tight associations with at least one of the pancreatic cancer related genes in that list." (PMID 33270085, 2021). "Data from THPA and patients with pancreatic cancer enrolled in our hospital also confirmed the prognostic value of PPP1CA, PPP1CB, PPP2CA, PPP2CB, PPP3CA, PPP3CB, and PPP6C at the protein level." (PMID 33270085, 2021). "Results of the present study suggest that PPP1CA, PPP1CB, PPP2CA, PPP2CB, and PPP3CA have deleterious effects but PPP3CB, PPP5C, and PPP6C have beneficial effects on pancreatic cancer." (PMID 33270085, 2021). "In recent years, it has been reported that PPP1CA, PPP1CB, PPP2CA, PPP2CB, and PPP3CA accelerate the progression of pancreatic cancer, while PPP3CB, PPP5C, and PPP6C hinder PAAD progression." (PMID 34125004, 2021). "In addition, only PPP3CB and PPP6C showed favorable prognostic values with regard to protein level, whereas PPP1CA, PPP1CB, PPP1CC, PPP2CA, PPP2CB, and PPP3CA showed unfavorable prognostic values in pancreatic cancer (P<0.05)." (PMID 33270085, 2021).
prostate carcinoma (2 papers, 2007 to 2014). A carcinoma that arises from epithelial cells of the prostate gland. "They found PPP2CB to be deleted in 23.5% of 145 primary prostate cancers analyzed by means of comparative genomic hybridization." (PMID 24503940, 2014). "Another five of 16 prostate cancer tumors showed PPP2CB deletion identified by array-CGH." (PMID 24503940, 2014). "Despite being down-regulated in primary prostate cancers, PPP2CB did not correlate with clinico-pathological factors." (PMID 24503940, 2014). "In contrast to PP1α, PPP2CB, a catalytic subunit of PP2A, did not correlate with the clinico-pathological factors analysed suggesting that PP2A does not play a prominent role in prostate cancer." (PMID 17146477, 2007).
atherosclerosis (1 paper, 2025). A disease characterized by the build-up of fatty material and calcium deposition in the arterial wall resulting in partial or complete occlusion of the arterial lumen. "Future studies should validate its clinical utility and explore PPP2CB-targeted therapies to support individualized atherosclerosis management." (PMID 40611318, 2025). "The present work pioneers efforts to systematically analyze the contribution of PPP2CB within the context of atherosclerosis-related lipid metabolism using a comprehensive approach that integrates clinical data, animal models, and cellular experiments." (PMID 40611318, 2025). "In the present study, elevated PPP2CB gene expression was observed in peripheral blood cells from patients with atherosclerosis, atheromatous plaques from atherosclerotic mice, and hyperlipidemic hepatic cells in vitro, compared to normal controls." (PMID 40611318, 2025). "Based on these observations, it was hypothesized that PPP2CB promotes hepatic lipid accumulation and contributes to atherosclerosis by interacting with LOX-1 receptor and activating the MAPK/ERK cascade." (PMID 40611318, 2025). "PPP2CB was found to promote lipid accumulation and LDL uptake via LOX-1/MAPK/ERK signaling, contributing to atherosclerosis progression." (PMID 40611318, 2025). "Second, while PPP2CB’s effect on early to mid-stage atherosclerosis was assessed, the 12-week high-fat diet model did not capture its potential influence on late-stage pathological features such as fibrosis and plaque rupture." (PMID 40611318, 2025). "Mechanistically, the study uncovered a novel interaction between PPP2CB and LOX-1 and demonstrated the downstream activation of the MAPK/ERK pathway, contributing new insights into the intracellular regulatory network of dyslipidemia-induced atherosclerosis." (PMID 40611318, 2025). "Recent findings suggest a potential role for PPP2CB, a catalytic subunit of PP2A, in disease-related signaling, while its contribution to atherosclerosis is not yet been unknown." (PMID 40611318, 2025).
bladder cancer (1 paper, 2019). "Among other Pi-specific hub genes: ADRBK1 is known to be involved in neuroinflammation and multiple sclerosis; FHL3 is involved in regulating integrin-mediated cytoskeletal events; PPP2CB is known to be involved in bladder cancer." (PMID 31536525, 2019).
chordoma (1 paper, 2014). Chordomas are rare malignant tumors arising from embryonic remnants of the notochord in axial skeleton. "We found ALG11 and PPP2CB to be up- and TMEM144 to be differentially regulated in large physaliferous MUG-Chor1 cells, hence being putative effector genes for chordoma cell development." (PMID 24503940, 2014).
colon cancer (1 paper, 2021). "qRT-PCR was performed from RNA extracted from 43 pairs of colon cancer and adjacent normal tissues to observe the relative expression levels of eight GRGs (P4HA1, STC2, CHPF2, PMM2, PGM2, ENO3, PPARGC1A, and PPP2CB)." (PMID 34422808, 2021).
colorectal cancer (1 paper, 2016). A primary or metastatic malignant neoplasm that affects the colon or rectum. "Additionally, the mutational frequency was >10% in 8 other TSGs in colorectal cancer: FAT4 (19%), TOPORS (15%), PPP2CB (13%), RASL11A (13%), PCDH9 (12%), PRDM2 (12%), LIFR (11%) and TGFBR2 (11%)." (PMID 26590405, 2016).
dyslipidemia (1 paper, 2025). "A potential regulatory association between dyslipidemia-driven PPP2CB upregulation and ApoE was indicated." (PMID 40611318, 2025). "Although the protein phosphatase 2 catalytic subunit beta (PPP2CB) is involved in post-transcriptional gene regulation, its role in AS-associated dyslipidemia is not well understood." (PMID 40611318, 2025).
hyperlipidemia (1 paper, 2025). "Notably, PPP2CB manipulation disrupted hyperlipidemia-induced LOX-1 expression." (PMID 40611318, 2025).
Infertility (1 paper, 2014). "Increased levels of PPP2cb may contribute to the observed meiotic arrest and infertility observed in Marf1−/− mice." (PMID 24755989, 2014).
liver cancer (1 paper, 2023). An epithelial or non-epithelial malignant neoplasm that arises from the liver. "We focused our siRNA screen on cell migration and thereby confirmed a metastasis suppressive role for MSRA, NAT1, PPP2CB, and DLC1 in liver cancer." (PMID 38134284, 2023).
renal tumour (1 paper, 2017). "CNAs of suppressor genes present in at least 5 renal tumour genomes linked PPP3CC, PPP2CB and RBX1 in 9/11/7 HRO tumours with 19/11/11 KEGG pathways." (PMID 28486536, 2017).
tumor (9 papers, 2007 to 2026). "PP2A is a well-conserved tumour suppressor and a frameshift mutation in PPP2CB could cause PP2A to lose functionality and cause disordered cell proliferation and a more aggressive cancer progression." (PMID 32857815, 2020). "Losses in the 8p23.1 region, which contains multiple genes related to immune function, T-cell regulation (TNKS, PPP2CB,) and tumor suppression (CSMD1, MSR), were enriched in MEITL (61% versus 7%, p = 0.02)." (PMID 41057685, 2026). "In summary, as the central transportation hub in tumor tissue, PPP2CB affects tumor cell migration by regulating EMT, and it also regulates the tumor immune microenvironment and affects tumor immunity by interacting with immune cells." (PMID 34579753, 2021). "The pro-inflammatory phenotype of miR-1246 in MSCs was independent of TNFα stimulations and mediated by direct targeting of the tumor-suppressors PRKAR1A and PPP2CB." (PMID 28159925, 2017). "The Hippo, PI3K/AKT, and tumor microenvironment signaling pathways, responsible for cell proliferation, migration, and invasion, were more enriched in differentially expressed predicted target genes (LATS2, NRAS, PPP2CB, etc.)in cells transfected with mimics of ISO-miR-1246_a and/or ISO-miR-1246_G." (PMID 38474054, 2024).
cancer (3 papers, 2020 to 2025). A tumor composed of atypical neoplastic, often pleomorphic cells that invade other tissues. "The prognostic model incorporates genes, such as YY2, PDHA1, SDC3, PPP2CB, and PDK3, all of which have been previously reported to influence cancer prognosis." (PMID 41235100, 2025). "In contrast, PPP2R2A was the most deleted gene found in > 20% of samples across 17 cancers, followed by the deletion of SLC2A4 in 16 cancers and five additional genes (FOXO3, PPP2CB, PPP2R2D, PPP2R5C and PPP2R5E) in 15 cancer types." (PMID 32807122, 2020).
cardiovascular disease (1 paper, 2025). "Nevertheless, further research efforts are warranted to uncover the expression patterns as well as functional implications of PPP2CB at the molecular, cellular, and tissue levels in cardiovascular disease." (PMID 40611318, 2025).
PPP2CB also shares sentences with these, for which no sentence is quoted: infection (1 paper); lung carcinoma (1); multiple sclerosis (1); ovarian carcinoma (1); pancreatic adenocarcinoma (1).